Y_RNA (Y RNA )
Gene: Miscellaneous RNA gene on chromosome 12 (42,454,720 to 42,454,821, forward strand). Ensembl gene ENSG00000207142.
Homologues: Orthologues: chimpanzee Y_RNA (100% identical), macaque Y_RNA (97% identical), guinea pig Y_RNA (94% identical), guinea pig Y_RNA (93% identical), guinea pig Y_RNA (91% identical). Paralogues in human: RNY3 (97% identical), Y_RNA (94% identical), RNY3P1 (93% identical), Y_RNA (93% identical), Y_RNA (92% identical), Y_RNA (91% identical), Y_RNA (90% identical), Y_RNA (89% identical), RNY3P14 (88% identical), Y_RNA (88% identical), RNY3P11 (87% identical), RNY3P16 (87% identical), and 99 more.